LINC01929 (long independently transcribed non-coding RNA 1929)
Synonyms: CTD-2171N6.1
Gene: Long non-coding RNA gene on chromosome 18 (55,105,903 to 55,128,662, reverse strand). Ensembl gene ENSG00000267013.
Diseases named in the same sentence as LINC01929 in open-access papers:
LINC01929 is named in the same sentence as 9 diseases in open-access papers, as found by Europe PMC text mining. Sharing a sentence is not in itself a finding about the gene and the disease. The quoted sentences say what the papers report.
bladder cancer (2 papers, 2022). "Overexpression of LINC01929 promoted bladder cancer development, while overexpression of miR-6785-5p inhibited bladder cancer development." (PMID 35646642, 2022). "It has been reported that LINC01929, which is highly expressed in advanced bladder cancer, upregulates the expression level of ADAMTS12 through competitive adsorption of miR-6875-5p, and based on this molecular mechanism, overexpressed miR-6875-5p inhibits the progression of bladder cancer." (PMID 36204659, 2022).
breast carcinoma (2 papers, 2024 to 2026). "Knockdown of LINC01929 in breast cancer cell lines reduced cell survival, cell cycle progression, inhibited tumor growth, and altered the expression of genes involved in growth, immune, and antigen presentation pathways." (PMID 41993692, 2026). "The knockdown of LINC01929 significantly inhibited breast cancer cell proliferation and induced cell cycle arrest." (PMID 39586790, 2024). "In conclusion, this research underscores the potential of LINC01929 as a pivotal player in cancer biology, particularly in breast cancer." (PMID 39586790, 2024).
lung carcinoma (1 paper, 2020). "When compared with the non-tumorigenic IMR-90, the expression of FEZF1-AS1, LIN00673 and LINC01214 was markedly higher in most lung cancer cell lines; the expression of PCAT6 and LINC01929 was strikingly lower and no clear trend was observed for the expression of NUTM2A-AS1." (PMID 32020063, 2020).
oral squamous cell carcinoma (1 paper, 2022). "LINC01929 functioned as a tumor-promoting molecule in oral squamous cell carcinoma by accelerating cell proliferation, migration, and invasion, and suppressing apoptosis, suggesting that it may be a novel target for cancer therapy." (PMID 35996496, 2022). "Previously, LINC01929 was identified as existing in the cytoplasm through a nuclear-cytoplasmic fractionation assay and that it may sponge miR-137-3p in oral squamous cell carcinoma cells." (PMID 35996496, 2022).
squamous cell carcinoma (1 paper, 2020). A carcinoma arising from squamous epithelial cells. "On the other hand, the expression of LINC00673 (p = 6.42 × 10–30), PCAT6 (p = 1.01 × 10–7), NUTM2A-AS1 (p = 3.69 × 10–5) and LINC01929 (p = 3.26 × 10–6) was significantly higher in squamous cell carcinomas than in adenocarcinomas." (PMID 32020063, 2020).
tumor (5 papers, 2020 to 2026). "We found that LINC01929 is associated with the proportion of macrophages in various tumours and negatively correlated with CD8+ T cells." (PMID 39586790, 2024). "Our analysis revealed that LINC01929 was weakly expressed in 3 tumour types and highly expressed in 14 tumour types, and low expression of LINC01929 was correlated with better clinical outcomes in 15 tumour types." (PMID 39586790, 2024). "Taken together, LINC01929 functioned as a tumor-promoting lncRNA via the miR-137-3p/FOXC1 axis in OSCC, suggesting novel targets for OSCC therapy." (PMID 33968763, 2021). "In vivo and in vitro experiments suggested that LINC01929 plays a key regulator in tumour growth." (PMID 39586790, 2024). "Tumour stage significantly associated with the expression of LINC00673 (p = 0.005), LINC01929 (p = 0.002), PCAT19 (p = 0.001), FENDRR (p = 8.33 × 10–6), SVIL-AS1 (p = 0.037), LANCL1-AS1 (p = 8.69 × 10–7), LINC00968 (p = 2.32 × 10–7) and ADAMTS9-AS2 (8.29 × 10–6) as determined by Kruskal–Wallis test." (PMID 32020063, 2020). "Furthermore, LINC01929 expression was correlated significantly with the TMB, MSI, immune checkpoint and immune cell infiltration across multiple tumour types." (PMID 39586790, 2024). "Through immune infiltration analysis, it was found that the expression of LINC01929 is positively correlated with macrophages and negatively correlated with CD8 T cells in various tumours, which suggested that it may act as a modulator of immune evasion, a hallmark of cancer." (PMID 39586790, 2024).
cancer (4 papers, 2020 to 2026). A tumor composed of atypical neoplastic, often pleomorphic cells that invade other tissues. "According to this study, it was observed that the LINC01929 gene, an important pan‐cancer biomarker, exhibits high expression across various types of cancer and is associated with poor prognosis." (PMID 39586790, 2024). "LINC01929 acts as a competitive endogenous RNA, regulating a cancer-promoting and immunosuppressive microRNA-mRNA network." (PMID 41993692, 2026). "This research focuses on the expression and functional implications of LINC01929 in pan‐cancer, aiming to unravel its potential biological mechanisms and clinical significance." (PMID 39586790, 2024).
LINC01929 also shares sentences with these, for which no sentence is quoted: adenocarcinoma (1 paper); non-small cell lung carcinoma (1).